CTLA4 (cytotoxic T-lymphocyte associated protein 4)
Diseases named in the same sentence as CTLA4 in open-access papers (continued):
Sharing a sentence is not in itself a finding about the gene and the disease.
tumor (continued). "Though, both checkpoint blockades (anti-CTLA-4 and PD-1/PD-L1) rescues anti-tumor T lymphocytes, they are thought to affect different phases of anti-tumor T cell responses." (PMID 33329567, 2020). "CTLA-4 plays a key role in regulating the T-cell system and is often used as suppressive immune molecules in tumor therapy." (PMID 33665205, 2020). "Strikingly, this approach combined with CTLA-4 blocking (anti-CTLA4) can inhibit immune-suppressive Tregs in tumors and was favorable for anti-tumor immunity." (PMID 32408880, 2020). "ACT with MART1-specific T cells combined with CTLA-4 blockade resulted in long-term T cell persistence and durable tumour regression in metastatic melanoma patients." (PMID 32183246, 2020). "Regardless, the function of PD-1 and CTLA-4 in antagonising key metabolic pathways in T cells are mechanisms tumours used to limit anti-tumour immunity, and provides an explanation for the capacity of T cells to be metabolically invigorated by ICB." (PMID 33092283, 2020). "MicroRNA miR-138 was suggested to function as a tumour suppressor and demonstrated to target CTLA-4 and programmed cell death 1 (PD-1) in CD4+T cells." (PMID 32054041, 2020). "It would seem that malignant B-cell CTLA-4, at least, is capable of dampening T-cell-mediated anti-tumor immune responses while paradoxically limiting B-cell proliferation and survival." (PMID 33384695, 2020). "Mice were treated as above with α-CTLA-4 and ISV + α-CTLA-4 targeting the right flank tumor and were compared with untreated mice or those receiving only α-CTLA-4." (PMID 32690669, 2020). "A preclinical study in mice reported that tumor-associated VEGF enhanced expression of PD-1 and other inhibitory checkpoints involved in CD8+ T cell exhaustion, such as CTLA-4, TIM-3, and LAG-3, and targeting VEGF reverted expression of inhibitory checkpoints." (PMID 32850419, 2020). "There is limited clinical data about dynamic changes in tumor TCR repertoire diversity upon anti-CTLA-4 monotherapy." (PMID 33163002, 2020). "To guarantee robust power to detect tumor CTLA-4 expression by assuring the highest tumor cell content, we selected tumors with at least 60% tumor purity, defined by the ESTIMATE algorithm (N = 783)." (PMID 32850353, 2020). "Consistent with previously data, administration of CTLA-4 mAbs after tumor challenge resulted in a reduced frequency of Foxp3+ cells in the B16-IL36 tumor." (PMID 32351508, 2020). "Our results demonstrated that the expression of inhibitory receptors (including PD1, CTLA4, LAG3, and TIM3) were positively correlated and were associated with certain types of T cells in tumor tissues, especially CD8+ Tcm and CD8+ T cells." (PMID 32728493, 2020). "PD-1, PD-L1 and CTLA4 are immune checkpoint molecules that downregulate T cell activation, allowing tumor cells to evade the host immune system." (PMID 33312694, 2020). "We found the up-regulation of cytotoxic cells, CD274 (PD-L1), PDCD1, CTLA-4, HAVCR2, IFN-γ, and so on in high-risk group, whereas opposite result was observed only in absolute tumor purity." (PMID 32537435, 2020). "In this study, mice underwent tumor resection, followed by adjuvant anti-CTLA-4 blockade or isotype-matched IgG on days 4, 7, and 10 after surgery." (PMID 32630247, 2020). "Our observations on CT26 syngeneic tumors treated with anti-PD-1 or anti-CTLA-4 suggest heterogeneous response at both the bulk tumor level and at the cancer clone level." (PMID 33059736, 2020). "Blocking PD-1, PD-L1 or CTLA4 improves T cell function and augments the host immune response, leading to enhanced tumor killing and inhibition of tumor growth." (PMID 33312694, 2020). "Nivolumab (anti-PD1) and ipilimumab (anti-CTLA4) are two of the most successful checkpoint inhibitors currently on the market and have clinically been shown to increase overall survival and tumor progression for inoperable metastatic melanoma." (PMID 32157600, 2020).
tumor (continued). "In the context of immunotherapy, the immunosuppressive role of host cell expressed IDO is supported by a striking delay in tumor growth in anti-CTLA-4 treated IDO knockout mice compared to WT mice." (PMID 33072086, 2020). "In the peripheral blood, the expression levels were the same as in the lymph node tissue with the tumor size was in 100 mm3, and there was a much higher level of both PD-1 and CTLA-4 in the small tumor sizes (such as 100 mm3) than in the big ones (* P < 0.05)." (PMID 32805718, 2020). "Specific isotypes of anti-CTLA-4 (aCTLA-4) mAbs [immunoglobulin G2a (IgG2a)] mediate the depletion of tumor-resident Tregs (trTregs) via antibody-dependent cellular cytotoxicity, although other isotypes (IgG1) do not." (PMID 32998971, 2020). "It was also reported that over-expression of CTLA-4 promotes the activation of the ERK1/2/MAPK pathway in different tumor types and stimulated T-cells." (PMID 32850353, 2020). "In preclinical studies, relevant studies have shown that anti-PD-1, anti-PD-L1, and anti-CTLA-4 can achieve tumor survival in 50%、20%, and 15% of mice respectively when treated with tumor model alone." (PMID 33679686, 2020). "This inhibitory agent stops CTLA-4 from inactivating T cells, therefore enhancing the activity of effector T cells against tumor cells." (PMID 32596146, 2020). "Among the IRGs filtered, the CTLA-4 promotes immune escape of tumor cells by competitively binding to CD80 and CD86, blocking T cell activation and anti-tumor immune response of the body." (PMID 33031392, 2020). "Overall, the flow cytometric and immunohistochemical analyses supported the uptake pattern of [64Cu]NOTA-CD8a in CT26 tumor-bearing mice subjected to XRT alone or in combination with anti-CTLA-4 therapy." (PMID 32086762, 2020). "Here we have found that, in addition to the expected expression of CTLA-4 on infiltrating lymphocytes, tumor cells from some patients, and cell lines, are also positive for the expression of CTLA-4 at the cell-surface." (PMID 32850353, 2020). "We investigated the effect of combining tumor-targeted NIR-PIT against the cell-surface antigen, CD44, which is known as a cancer stem cell marker, with a systemic CTLA4 immune checkpoint inhibitor in three syngeneic tumor models (MC38-luc, LL/2, and MOC1)." (PMID 32937841, 2020). "An oncolytic NDV expressing an anti-CTLA4 antibody as a radio-enhancing agent synergized with standard radiation to boost tumor repression." (PMID 33172438, 2020). "IC inhibitors (ICIs), i.e., antibodies targeting CTLA-4, PD-1, or PD-L1, are used as immunomodulatory agents to interfere with the CTLA-4:B7-1/2 or PD-1:PD-L1 axes and to help to overcome tumor-immune escape with very different efficacy." (PMID 32276524, 2020). "CTLA4 mAbs have been shown to enhance the anti-tumor immunity in humans by blocking activation of FOXP3+CD4+ Tregs." (PMID 32733457, 2020). "The anti-CTLA-4 ICIs (Tremelimumab, Ipilimumab) enhance anti-tumor immunity by reducing Treg frequencies, increasing activation threshold, and preventing anergy of T cells." (PMID 33718121, 2020). "In summary, preclinical models have provided a proof-of-concept that ICB with anti-CTLA-4 and/or anti-PD-1, either as monotherapy or in conjunction with standard-of-care treatments, improves tumor outcome." (PMID 32014107, 2020). "The distribution of grade 3–5 irAEs across all tumour types in the main clinical trial testing anti-CTLA-4 antibodies indicates that these side effects mainly occur in the gastrointestinal tract." (PMID 32183814, 2020). "CTLA-4 blockade stimulates anti-tumor immunity by increasing the expansion of CD45RO+ICOS+PD-1lowTBET+ Th1-like CD4+ effector and also exhausted-like CD8+ T cells." (PMID 33519807, 2020). "Nevertheless, single blockage of VISTA was insufficient to reduce tumor growth compared to a simultaneous blockage of CTLA-4 and VISTA, recommending combined ICP-targeting in HNSCC." (PMID 33396515, 2020).
tumor (continued). "Tumor-bearing mice receiving IL-15 with antibodies to CTLA-4 and PD-L1 manifested marked prolongation of survival compared to mice receiving IL-15 with either agent alone." (PMID 32508818, 2020). "The CD44-targeted NIR-PIT group and combination group showed significantly greater tumor reduction compared to the CTLA4 mAb group." (PMID 32937841, 2020). "This has already been shown in preclinical models for agonist OX40 or anti-CD40 antibodies, where the addition to the combination of an anti-CTLA-4 antibody and a vaccine enhanced tumor response in a mouse model." (PMID 32325898, 2020). "One promising treatment avenue is immune checkpoint inhibition (ICI) where key negative regulators of cytotoxic lymphocyte activity are inhibited, such as CTLA-4 and PD-1, to improve the immune response against the tumor." (PMID 33034643, 2020). "Over the past few years, several drugs, like PD-1, PDL-1 and CTLA-4 antibodies, have been developed for tumor immunotherapy with gratifying results." (PMID 33148302, 2020). "Treatment of tumor-bearing mice with Sema4D mAb in combination with either CTLA-4 or PD-1 blockade enhanced the rejection of tumors or tumor growth delay, resulting in prolonged survival with either treatment." (PMID 32443699, 2020). "The hypermethylation-derived silencing of CTLA-4 and PD-1 was also observed in baseline tumor biopsies compared to their pair-matched tissues in NSCLC patients." (PMID 31968651, 2020). "Patient preconditioning with the anti-CTLA-4 antibody ipilimumab was employed to increase tumor infiltration of tumor reactive lymphocytes before tumor tissue harvest for TIL production." (PMID 32547707, 2020). "Studies of related peptides on CTLA-4, PD-1, and PD-L1 have demonstrated the ideal functional activities in tumor immunotherapy." (PMID 33084973, 2020). "While in interstitial lymphocytes, CTLA-4 expression was detected in the cell membrane and cytoplasm, in tumor cells, the staining was exclusively cytoplasmic." (PMID 32123292, 2020). "CTLA-4 antibodies enhance anti-tumor activity by suppressing Treg activity or reducing the number of Tregs in the tumor tissue via antibody-dependent cellular cytotoxicity (ADCC) due to CTLA-4 overexpression on Tregs." (PMID 31900651, 2020). "During cancer development anti-tumor immunity is suppressed and immunotherapies targeting CTLA-4 and PD-1 signaling axes have been developed to reactivate T cells to induce immune-mediated tumor eradication." (PMID 33193345, 2020). "A new class of mAbs targets so-called immune checkpoint pathways (e.g. PD-1/PD-L1 and CTLA-4) in order to stimulate anti-tumor immune responses." (PMID 33033688, 2020). "First-generation ICBT primarily targets the CD28/CTLA-4 and the PD-1/PD-L1 signaling pathways, to revitalize functionally suppressed T cells in tumor conditions (detailed mechanisms were summarized in the previous reviews)." (PMID 32380703, 2020). "In TCGA dataset, CTLA4 was highly expressed in tumor tissues (N = 494) compared to normal tissues (N = 68, p < 0.001), and the paired test also confirmed that CTLA4 was highly expressed in ccRCC (N = 68, p < 0.001)." (PMID 33117084, 2020). "The tumor responses according to the Response Criteria in Solid Tumors (RECIST) criteria varied from 5.7% to 11.0% in the anti-CTLA-4 treatment arms." (PMID 33092131, 2020). "Partial blocking of CTLA-4 with Abs resulted in regression of tumour in mice displaying partially immunogenic tumours." (PMID 32645977, 2020). "We only studied samples with a predicted tumor purity higher than 60%, and CTLA-4 expression profiles were adjusted using the lymphocyte enrichment scores and tumor purity values." (PMID 32850353, 2020). "The combination of a HSP90 inhibitor and an anti-PD-1, PD-L1, and CTLA-4 antibodies have already demonstrated anti-tumor efficacy in preclinical and CRC clinical trials." (PMID 33329567, 2020).
tumor (continued). "CTLA4 and PD-1 blockade, although both intended to enhance anti-tumor immunity, produce distinct immunoregulatory patterns that vary in effectiveness with each tumor model." (PMID 32937841, 2020). "We applied the Immune Score (IS), which infers the response to anti-CTLA-4 immunotherapies in accordance with tumor CTLA-4 status." (PMID 32850353, 2020). "They reported that TMB and expression of cytotoxic cells in the tumor microenvironment were significant predictors of response to CTLA-4." (PMID 33080912, 2020). "Targeting the immune checkpoints “programmed death ligand-1” (PD-L1), “programmed cell death protein-1” (PD-1) and “cytotoxic T-lymphocyte associated protein 4” (CTLA-4) with antibodies leads to T-cell activation and anti-tumor immune response." (PMID 31900121, 2020). "Mice challenged with tumors and subsequently administered anti-CTLA4 DMAb showed clearance in eight out of ten animals, with all demonstrating immunological memory after re-challenge by clearing 100% of the tumor." (PMID 32157600, 2020). "We observed a low variability of CTLA-4 expression between different patient samples, except one tumor with a very high and one sample with a very low expression of CTLA-4." (PMID 31960110, 2020). "CTLA4 mAb group showed significantly greater tumor volume than combination group at 17, 21, 24 and 28 days after NIR-PIT (p < 0.05, Tukey–Kramer test)." (PMID 32937841, 2020). "Research has shown that CTLA-4 is also expressed on the surface of tumour cells and inhibit T cell activation and prevent anti-tumour immunity." (PMID 32645977, 2020). "The isolated tumors were evaluated for changes in tumor volume following treatment with anti-CTLA-4, changes in immune cell subpopulations, and the expression of critical immune checkpoints by flow cytometry." (PMID 32805718, 2020). "The blockade of the PD-1/PD-L1 and/or of the CTLA-4/B7 axes by antibodies reinstates T cell function and anti-tumor cytotoxic activity in the tumor microenvironment." (PMID 33167582, 2020). "Deeper researches demonstrated that CTLA4 regulates T cell activation and was significantly linked to TIL-abundant tumor microenvironment (TME), but was accompanied by an immunosuppressed phenotype." (PMID 33117084, 2020). "In this study, we extended our analyses to include pretreatment tumor samples derived from patients who received combination (anti-PD-1 plus anti-CTLA-4) immunotherapy." (PMID 33202676, 2020). "In this study, we extended our previous study of SEMA3s to SEMA3 receptors to test the correlation between their expression and tumor infiltrates, as well as their association with the expression of immune blockade molecules PD1/PDL1 and CTLA-4 in cancer TME." (PMID 32640719, 2020). "We then treated the recipient mice with control IgG, anti-PD-1, or anti-CTLA-4, and observed significantly reduced tumor growth upon ICB treatment." (PMID 33059736, 2020). "For instance, synergistic effects on tumor control for 4-1BB agonist with the PD-1 or CTLA-4 blockade in the human and animal setting were found." (PMID 32391001, 2020). "Despite the great success of anti-CTLA-4 and anti-PD-1/PD-L1 therapy, due to the complex adjustment of anti-tumor immunity in the tumor microenvironment, only a small percentage of patients benefit from ICB." (PMID 32992835, 2020). "Surgical resection of CLNs significantly decreased the immune infiltration and abolished the tumor regression induced by anti-PD-1/CTLA-4 combination therapy." (PMID 32094452, 2020). "In preclinical models, inhibition of Tim-3 by anti-Tim-3 monoclonal antibodies, either as monotherapy or in combination with anti-PD-1 or anti-CTLA-4, has shown improved anti-tumor effects and growth inhibition." (PMID 32679922, 2020). "By blocking the CTLA4/ligands, interaction T cells remain active, thus being able to recognize and kill tumor cells." (PMID 32823961, 2020).
tumor (continued). "We found that stathmin was significantly associated with VEGF and vascular proliferation as well as with the immune response markers FOXP3, CTLA4, PD-L1 and PD-1 in tumour tissues." (PMID 32076022, 2020). "Tregs, found in tumor tissue and draining lymph nodes, have high expression of CTLA-4 and Lag-3 that facilitate suppression of dendritic cells (DCs) and T cells through direct cell-to-cell contact." (PMID 33339195, 2020). "Our data further demonstrated that depletion of Treg by CTLA-4 mAbs unleashed the power of IL36-mediated tumor immunotherapy." (PMID 32351508, 2020). "Combination anti-CTLA4 and anti-PD-1 work synergistically by increasing IFNγ signaling, which in turn increases IL-7 signaling, resulting in superior tumor eradication." (PMID 32133005, 2020). "PD-1 and CTLA-4 are immune checkpoint receptors that transmit an inhibitory signal to T-cells after ligation and contribute to exhaustion of tumor-infiltrating T-cells." (PMID 32366834, 2020). "The FDA already approved specific monoclonal antibodies, known as ICIs, active against PD-1 (nivolumab), PD-L1 (pembrolizumab), and CTLA-4 (ipilimumab) for several types of tumor, such as melanoma, kidney, bladder and lung cancers, and Hodgkin lymphoma." (PMID 33255336, 2020). "The study of CTLA-4 expression and function has so far been centered on hematopoietic lineages and anti-tumor responses." (PMID 33384695, 2020). "CTLA-4 antibody induces anti-tumor immunity by blocking Foxp3+Treg cells in the tumor microenvironment and AKT phosphorylation pathway, effectively amplifying T cells and enhancing the anti-tumor effect." (PMID 33033520, 2020). "The outgrowth of TILs from tumor fragments was higher in 12 of 14 patients when cultured with anti-CTLA-4 antibody." (PMID 32127601, 2020). "Altogether, these results show a significant correlation between primary resistance to anti-CTLA-4 or anti-PD-1 and tumor MHC I/II expression, which has a strong potential as a predictive biomarker in ICI therapies." (PMID 32992737, 2020). "Since one of the antitumor mechanisms of CTLA-4 mAbs is through depletion of tumor infiltrating Treg, we studied the effect of combination therapy of CTLA-4 mAbs and IL36." (PMID 32351508, 2020). "Upregulated level of VISTA on tumor-infiltrating lymphocyte and M2-macrophages have been illustrated in patients with prostate cancer who received the treatment of anti-CTLA-4 mAb." (PMID 32508809, 2020). "Anti-PD-1/PD-L1 blockade primarily affects the immune activity in tumor environment, whereas anti-CTLA-4 therapy restores the immune activity throughout the lymph tissues." (PMID 33102516, 2020). "CTLA-4+ tumor-infiltrating NK cells embody an anti-CTLA-4 monoclonal antibody-based prospective immunotherapeutic target." (PMID 32117298, 2020). "In murine studies, the effects of anti-CTLA-4 monotherapy on tumor TCR diversity are model-dependent." (PMID 33163002, 2020). "Combinations of anti-PD-1/PD-L1 and anti-CTLA-4 mAb have been investigated in various tumor types, including HCC." (PMID 32878115, 2020). "Another humanized anti-CTLA-4 antibody, tremelimumab, has been shown to elicit favorable responses in clinical trials against different tumor types." (PMID 31911758, 2020). "The addition of RX-5902 to CTLA-4 or PD-1 inhibitors resulted in decreased tumor growth in the 4 T1 and human immune system and MDA-MB-231 xenograft models." (PMID 33148223, 2020). "These neoantigens can be potent tumour-rejection antigens, appear to be the driving force behind responsiveness to anti-CTLA-4 and anti-PD1/L1-based therapies and have been used to develop personalized vaccines." (PMID 32019478, 2020). "On the other hand, the combination of CSF1R blockade with either anti-PD1 or anti-CTLA4 initiated tumor regression." (PMID 32867025, 2020). "MDSC tumor-infiltration is mediated by CSF-1 and the combination of CSF-1/CSF-1R signalling inhibition with anti-CTLA-4 has been recently proposed." (PMID 32423420, 2020).